CPE (carboxypeptidase E)
Diseases named in the same sentence as CPE in open-access papers (continued):
Sharing a sentence is not in itself a finding about the gene and the disease.
depression (3 papers, 2014 to 2022). "Our findings indicate that this human CPE mutation could result in neurodegeneration, memory deficits and depression linked to AD." (PMID 27922637, 2016). "In addition to the endocrinological abnormalities, impairments in cognitive function and depression-like behaviors were observed in transgenic mouse models with CPE mutations suggesting the critical role of CPE in neurodegenerative and neuropsychiatric disorders." (PMID 35711734, 2022). "However, other human CPE mutations and SNPs exist, that could give rise to dementia and depression, given the link between CPE/NF-α1 and cognitive function." (PMID 27922637, 2016). "Animal studies revealed that rosiglitazone exerted its anti-depressant effect by upregulating hippocampal CPE expression and neurogenesis, suggesting a possible role of NFα1/CPE in the treatment of depression." (PMID 35711734, 2022). "Collectively, these studies showed that introduction of this mutated human CPE gene into a transgenic mouse model gave rise to neurodegeneration, impairment of memory, as well as depressive-like behavior, indicating the pivotal role of NFα1/CPE in neurodegenerative diseases and depression." (PMID 35711734, 2022). "In this mini-review the functions and potential therapeutic use of a newly discovered trophic factor, Neurotrophic factor-α1 (NF-α1), also known as Carboxypeptidase E (CPE), in depression and neuroprotection are discussed." (PMID 35711734, 2022). "The existence of a similar CPE mutant protein in humans suggests that the mutation is not unique to one individual and that such a mutant protein might also give rise to neurodegenerative disease and depression." (PMID 27922637, 2016).
hyperproinsulinemia (3 papers, 2013 to 2024). "Proinsulin processing includes removal of several C-terminal basic amino acids and is performed principally by the exopeptidase carboxypeptidase E (CPE), and mutations in CPE or other prohormone convertase enzymes (PC1/3 and PC2) result in hyperproinsulinemia." (PMID 37967211, 2023).
hypogonadotrophic hypogonadism (3 papers, 2017 to 2021). "Both Cpe knock out mice models and polymorphism studies in humans support the role of CPE in endocrinological defects, such as obesity, hypothyroidism and hypogonadotropic hypogonadism, which are present in our cases." (PMID 32936766, 2021).
liver cancer (3 papers, 2019 to 2022). An epithelial or non-epithelial malignant neoplasm that arises from the liver. "5’/3’ RACE were carried out separately in order to determine the nucleotide sequence of possible isoforms and splice variants of the CPE gene in human liver cancer cell HCC97H and ovarian cancer cell CAOV3." (PMID 31798768, 2019). "The expression of CPE was related to the recurrence survival rate and pathological stage of liver cancer, suggesting that the expression level of CPE could predict the prognosis of tumor." (PMID 35686102, 2022).
osteoporosis (3 papers, 2020 to 2024). A condition of reduced bone mass, with decreased cortical thickness and a decrease in the number and size of the trabeculae of cancellous bone (but normal chemical composition), resulting in increased fracture incidence. "Moreover, bioinformatics analysis identified CPE as a pivotal hub gene among differentially expressed mRNAs linked to osteoporosis." (PMID 39526243, 2024). "A novel eQTL association relevant to osteoporosis was identified in this study for the CPE gene." (PMID 32216834, 2020).
amyloid (2 papers, 2023 to 2025). "Furthermore, a direct dose-dependent correlation between CPE overexpression and the decrease of amyloid plaque formation in the hippocampus was found." (PMID 41291954, 2025).
Hydrocephalus (2 papers, 2008 to 2023). Hydrocephalus is an active distension of the ventricular system of the brain resulting from inadequate passage of CSF from its point of production within the cerebral ventricles to its point of absorption into the systemic circulation. "Knockout of genes expressed in the CPe, such as E2f5, a member of a family (E2f1–E2f6) of transcriptional regulators, FoxJ1, a member of the forkhead-box (Fox)/winged helix gene family, and p73, have been associated with hydrocephalus." (PMID 19114013, 2008). "We found that total TRPV4 abundance did not change with regards to the previously identified CPe isoforms and glycosylation products in response to hydrocephalus or drug treatment, consistent with the findings in our previous TRPV4 antagonist treatment study." (PMID 37596666, 2023).
Hyperinsulinemia (2 papers, 2015 to 2020). An increased concentration of insulin in the blood. "Carboxypeptidase E (CPE) is involved in the biosynthesis of various neuropeptides and hormones in the endocrine and nervous systems, and is associated with hyperinsulinemia and insulinoma." (PMID 32602849, 2020).
lung carcinoma (2 papers, 2019 to 2022). "N-terminal-truncated carboxypeptidase E represses E-cadherin expression by stabilizing the Snail-HDAC complex in lung cancer." (PMID 35686102, 2022).
neuroendocrine tumors (2 papers, 2011 to 2019). "Eight genes (CHGA, CPE, ENO2, INSM1, PTPRN2, SERPINA10, and SLC18A1/2) that have been previously identified as markers of neuroendocrine tumors were confirmed in this study to be altered." (PMID 21853033, 2011).
alcoholism (1 paper, 2017). "CPE has been identified in prior GWA studies on alcoholism, and it encodes the enzyme carboxypeptidase E, which activates neuropeptides, proteins crucial to communication among neurons." (PMID 28361705, 2017).
C. perfringens infections (1 paper, 2016). "However, further research is required to identify the exact role of NetE and CPE in the pathogenesis of netF-positive C. perfringens infections." (PMID 26859667, 2016).
carcinoid tumor (1 paper, 2007). A slow growing neuroendocrine tumor, composed of uniform, round, or polygonal cells having monotonous, centrally located nuclei and small nucleoli, infrequent mitoses, and no necrosis. "Another gene, CPE, is relatively down-regulated in the three poor-outcome samples of carcinoid tumors, and takes part in producing angiogenic factors upon the maturation of follicle stimulating hormone." (PMID 17411443, 2007).
cataract (1 paper, 2023). Partial or complete opacity of the crystalline lens of one or both eyes that decreases visual acuity and eventually results in blindness. "Moreover, inhibition of ACC can increase the intracellular acetyl-CoA level and stimulate the influx of calcium into the cells, which in the lens have been demonstrated to possibly be responsible for carboxypeptidase E activation and formation of a truncated form of αB-crystallin in cataracts." (PMID 37511188, 2023).
Chronic colitis (1 paper, 2020). A chronic inflammatory disease of the large intestine (colon, cecum and rectum). "Moreover, Bar et al40 found that CPE deficiency exacerbated experimental chronic colitis." (PMID 32570281, 2020).
colitis (1 paper, 2014). Inflammation of the colon. "The major finding here was a significantly more severe phenotype of colitis in cpe−/− mice as shown by MEICS, DAI and histology, indicating that CPE deficiency modulates the susceptibility of respective mice to experimental colitis." (PMID 25051500, 2014).
coronary atherosclerosis (1 paper, 2017). Atherosclerosis of the coronary vasculature. "In coronary atherosclerosis studies, point mutations of the CPE gene were associated with the disease from Chinese patients." (PMID 28114332, 2017).
coronary heart disease (1 paper, 2022). "In addition, CPE has been shown to be a multifunctional protein, which plays an important role in regulating the balance of endocrine and nervous system, as well as the occurrence of coronary heart disease (CHD)." (PMID 35340224, 2022).
COVID-19 (1 paper, 2024). A disease caused by infection with severe acute respiratory syndrome coronavirus 2. "These cases highlight the independent acquisition of CPE genes in patients with severe COVID-19 and antimicrobial selective pressures resulting in significant morbidity and mortality." (PMID 39483326, 2024).
Insulin resistance (1 paper, 2025). Increased resistance towards insulin, that is, diminished effectiveness of insulin in reducing blood glucose levels. "Further regulatory network analysis revealed that insulin resistance and sensitivity pathways were modulated through key genes, including IRS2, CPE, ADRB2, NR4A3, and FGF19." (PMID 40969325, 2025).
keloid (1 paper, 2025). An irregularly shaped, elevated mark on the skin caused by deposits of excessive amounts of collagen during wound healing. "We then focused on comparing the expression differences of IGFBP2+ fib marker genes (IGFBP2, FGFBP2, OLFML2A, CPE, APOD, SLC7A2) between keloids and normal controls." (PMID 39902627, 2025). "IGFBP2+ fibs are distinguished by the expression of marker genes including IGFBP2, FGFBP2, OLFML2A, CPE, APOD, and SLC7A2, which are markedly upregulated in normal skin tissue relative to keloid tissue." (PMID 39902627, 2025).
Lipedema (1 paper, 2022). Disorder of adipose tissue characterized by symmetric and bilateral enlargement of the lower extremities due to abnormal deposition of subcutaneous fat often in obese women. "An association of lipedema to carboxypeptidase E protein (CPE) has also been confirmed by a genome-wide association study (GWAS)." (PMID 36551837, 2022).
myelomeningocele (1 paper, 2020). Myelomeningocele is the most severe form of spina bifida. "The carboxypeptidase E (CPE) gene on chromosome 4, which may affect binding of WNT3A to the target cell’s receptor, associated with myelomeningocele in the MA population." (PMID 32970752, 2020).
Neurodevelopmental delay (1 paper, 2021). "Cases presented in this study showed severe neurodevelopmental delay that may be linked to a loss of enzymatic activity of CPE and may be linked to defective cortical neuron development." (PMID 32936766, 2021).
obesity syndrome (1 paper, 2021). "Together with the findings from a previous case, CPE can be considered as a candidate gene for a new monogenic obesity syndrome." (PMID 32936766, 2021).
osteoarthritis (1 paper, 2021). A noninflammatory degenerative joint disease occurring chiefly in older persons, characterized by degeneration of the articular cartilage, hypertrophy of bone at the margins and changes in the synovial membrane. "In addition, the comparison between our data and osteoblasts from mice cultured in vitro revealed that several genes (e.g., SLPI, MARCKS, CPE etc.), which are not correlated with osteoarthritis pathogenesis, show fundamental differences of expression levels between human and mouse osteoblasts." (PMID 34428745, 2021).
skin aging (1 paper, 2025). The gradual irreversible changes in structure of skin that occur as a result of the passage of time.. "Studies on extensive bioinformatics analyses and experimental verification have shown that carboxypeptidase E (CPE) is a promising biomarker and potential therapeutic target for skin aging." (PMID 40822678, 2025).
status epilepticus (1 paper, 2025). Status epilepticus is defined as a continuous seizure lasting more than 30 min, or two or more seizures without full recovery of consciousness between any of them. "Hippocampal delivery of the carboxypeptidase E gene has been shown to prevent neurodegeneration in male mice with Alzheimer’s disease, while Cpe knockout mice subjected to stress showed a loss of hippocampal CA3 neurons similar to that produced by status epilepticus." (PMID 40076950, 2025).
sudden infant death syndrome (1 paper, 2019). Unexpected death in infancy which remains unexplained following autopsy, review of the medical history, and investigation of the death circumstances and death scene. "CPE is a pore-forming toxin produced by C. perfringens type F and is responsible for food poisoning, antibiotic-associated diarrhea (ADD), sporadic diarrhea (SD), and sudden infant death syndrome (SIDS) in humans." (PMID 31514424, 2019).
thyroid tumor (1 paper, 2021). A benign or malignant neoplasm affecting the thyroid gland. "Local injection of these recombinant CPE mutants strongly reduced growth of Cldn1-expressing thyroid tumors in CDX models." (PMID 34503203, 2021).
tubular adenoma (1 paper, 2020). A usually polypoid neoplasm arising from the glandular epithelium. "CPE gene was amplified by PCR in 11 out of 12 SSA/P-D cases, in only 1 out of 25 SSA/P cases, and in none of the normal mucosa and tubular adenomas." (PMID 32481659, 2020).
tumor (23 papers, 2012 to 2026). "Besides the full length wild-type CPE (WT-CPE), a 40 kDa splice variant of CPE (CPE-ΔN) has been cloned and shown to promote tumor cell proliferation and invasion, by a distinct mechanism." (PMID 35328535, 2022). "Overexpression of this 40kDa CPE-ΔN variant up-regulated expression of multiple metastatic genes encompassing different signaling pathways, suggesting potentially an important role of CPE-ΔN in tumor metastasis." (PMID 31798768, 2019). "A functional analysis of tumor-associated proteins revealed reduced expressions of several proteinases, including dipeptidyl peptidase 4 (DPP4), carboxypeptidase E (CPE) and prostate specific antigen (KLK3) in AG and metastatic PCa." (PMID 34556748, 2021). "A functional analysis of tumor-associated proteins revealed the reduced expression of several proteinases, including dipeptidyl peptidase 4 (DPP4), carboxypeptidase E (CPE) and prostate specific antigen (KLK3), particularly in AG and metastatic PCa." (PMID 34556748, 2021). "Among the ones known to have tumor suppressive functions, we have focused on carboxypeptidase C (CPE), phosphoenolpyruvate carboxykinase 1 (PCK1), and phospholipase C-like 1 (PLCL1)." (PMID 32762776, 2020). "Carboxypeptidase E (CPE) has recently been described as a multifunctional protein that regulates proliferation, migration and survival in several tumor entities." (PMID 28978054, 2017). "Therefore, high levels of CPEB4 seem to be required for the oncoselective behaviour of the engineered virus and to prevent the CPE-mediated translational repression observed in non-tumour cells." (PMID 28300077, 2017). "However, an N-terminal truncated isoform of CPE (CPE-ΔN) was found to drive tumor progression in different types of cancer." (PMID 23209762, 2012). "Out of the 95 patient samples that were analyzed for protein expression of CPE-WT and CPE-∆N using Western Blot and IHC, it was observed that while WT-CPE was expressed at similar levels in tumor tissue and peri-carcinoma tissues, CPE-∆N was prominently expressed only in the tumor tissue." (PMID 31731578, 2019). "When the same analyses were done using PEA Oncology II profiling data, 10 proteins correlated to tumor stage (P < 0.05), for example, CD160, TNFRSF4/OX40L, XPNPEP2, SPARC, MAD homolog 5/SMAD5, CPE, hK8/KLK8, WIF‐1, TCL1A, and MIC‐A/B." (PMID 33768639, 2021). "Although CPE, a prohormone/proneuropeptide processing enzyme, has been reported to be elevated in CRC, its role in tumor development remains poorly understood." (PMID 24006921, 2013). "Together with the tumor-suppressing proteins such as CALR, ENO1, HSP, MSN, and UBC, which were enriched in tumor-suppressive CM, six recombinant proteins, such as HISTONE H4, PPIB, GJA1, CPE, S100A11, and PCOLCE, were identified as extracellular tumor-suppressing proteins." (PMID 36943734, 2023). "Accordingly, the CPE-regulated virus maintains its oncolytic capacity in tumour cells while significantly reducing its damage to non-tumour tissues, which is mainly in the liver as this is the target organ of adenovirus sequestration on intravascular delivery." (PMID 28300077, 2017).
cancer (21 papers, 2012 to 2024). A tumor composed of atypical neoplastic, often pleomorphic cells that invade other tissues. "Because several of the claudin subtypes that are overexpressed in human cancers are also CpE receptors, CpE is being actively investigated for translational applications and therapies in cancer." (PMID 35269525, 2022). "Previous studies have indicated that carboxypeptidase E (CPE) plays a role in promoting tumorigenesis in many cancer types." (PMID 35528956, 2021). "A 40kDa CPE-ΔN band was observed in cell lysates from HCC97H (liver) and COAV3 (ovarian) cancer cell lines using a BD anti-CPE antibody directed at amino acids 49-200 of CPE." (PMID 31798768, 2019). "Our data indicated that the overexpression of approximately equivalent amounts of CPE-WT and CPE-ΔN protein in Panc-1 cells, both significantly enhanced the proliferation of these cancer cells." (PMID 31731578, 2019). "From this limited gene list, carboxypeptidase E (CPE), fatty acid binding protein 7 (FABP7) and peroxisomal membrane protein 2 (PXMP2) were all previously found to be associated with human cancer." (PMID 29062039, 2017). "For oncolytic adenoviruses, insertion of CPE regulatory sequences in the 3′-untranslated region of the E1A gene provides oncoselectivity, with full potency in cancer cells but attenuated in normal tissues." (PMID 28300077, 2017). "Full-length CPE in HCC and other cancer cells is ~2.4 kb, but whether this 1.2 kb transcript of CPE mRNA could be successfully translated to yield a functional protein awaits future studies." (PMID 35328535, 2022). "The finding of a positive correlation of CPE mRNA copy numbers with malignancy suggests that circulating exosomal CPE could potentially serve as a useful biomarker to detect cancer in patients." (PMID 35328535, 2022). "Based on our results and others’ reports, there is an indication that CPE activities regulating signaling and bioenergetics in mesenchymal versus neuronal versus cancer cells may have opposite effects." (PMID 32995694, 2020). "We show that engineering adenoviruses with CPE regulatory elements, to control E1A expression post-transcriptionally, resulted in attenuated viral activity in normal cells while maintaining, or even increasing, potency in cancer cells." (PMID 28300077, 2017). "To elucidate the mechanism by which CPE-ΔN protects neurons, we searched for the activation of potential downstream target genes that are known to be involved in cell survival, since CPE-ΔN is present and functions in the nucleus to up-regulate gene transcription in cancer cells." (PMID 25426952, 2014). "Therefore, whether CPE plays a role in cancer immunity needs to be discussed further." (PMID 37880378, 2023). "Here, the authors show that the insertion of CPE regulatory sequences in the 3′ UTR of the E1A viral gene induces oncoselectivity, with oncolytic potency in cancer cells but attenuated toxicity in normal tissues." (PMID 28300077, 2017). "Three proteins (CPE, S100A11, and PCOLCE) are reported tumorigenic in OS and/or other cancer." (PMID 36943734, 2023). "Carboxypeptidase E (CPE), a member of the pro-protein convertases, which are involved in the maturation of protein precursors, has recently been reported as elevated in many types of cancer." (PMID 24006921, 2013). "Independent of its enzymatic activity, CPE may also act as a secreted factor with divergent roles in neuroprotection and cancer growth; however, its role in the regulation of bone mass and skeletal cell differentiation is unknown." (PMID 32995694, 2020).
neurodegenerative disease (6 papers, 2016 to 2023). A disorder of the central nervous system characterized by gradual and progressive loss of neural tissue and neurologic function. "A previous study demonstrated that a mutation in carboxypeptidase E was associated with the development of neurodegenerative diseases, suggesting that processing of neuropeptides plays a key role in neural function." (PMID 31323047, 2019). "As ER stress induced apoptosis has been implicated in various neurodegenerative diseases, the loss of function mutation in the CPE gene is likely to be involved in neurological disorders." (PMID 28114332, 2017).